NLRP3 (NLR family pyrin domain containing 3)
Diseases named in the same sentence as NLRP3 in open-access papers (continued):
Sharing a sentence is not in itself a finding about the gene and the disease.
neurological diseases (continued). "The NLRP3 inflammasome plays a key role in the development of inflammatory responses in the central nervous system, and its hyperactivation mediates the activation of downstream signaling pathways involved in various neurological diseases." (PMID 34046147, 2021). "This article reviews the relationship between NLRP3 inflammasome and nervous system diseases." (PMID 34526897, 2021). "Additionally, it provides more data support for TXNIP/NLRP3 as a potential target for treating neurological diseases." (PMID 34348577, 2021). "Findings suggest neuronal NLRP3 inflammasome activity may contribute to neuroinflammation observed during normal aging and the progression of neurologic disorders." (PMID 32680528, 2020). "In fact, recent publications suggest a new role for NLRP3 in the context of neurological disorders." (PMID 31892810, 2019). "Besides the NLRP3 inflammasome, NLRC4 inflammasome was also shown to be implicated in neurological diseases." (PMID 31892810, 2019). "This review gives an overview of the established functions of the NLRP3 inflammasome in mediating inflammation in macrophages and describes its recently discovered roles in neurological disorders in promoting neuroinflammation, as well as modulating key proteins mediating the disorders." (PMID 31892810, 2019). "The NOD-like receptor protein 3 (NLRP3) inflammasome may regulate the inflammatory process of microglia in several neurological diseases, but its role in CM is largely unknown." (PMID 30971286, 2019). "The activation of NLRP3, nucleotide oligomerization domain (NOD)-like receptor protein 1 (NLRP1), and NLR family CARD domain containing 4 (NLRC4), and the absence of Melanoma 2 (AIM2) inflammasomes are all associated with various neurological diseases." (PMID 31417409, 2019). "Moreover, emerging studies have revealed the involvement of NLRP3 signaling in several neurological disorders." (PMID 28337127, 2017). "Studies have shown that the activation of NF‐κB can also mediate the abnormal activation of NLRP3 inflammasomes in microglia and release the proinflammatory factors IL‐1β and IL‐18 outside the cell to participate in the occurrence and development of a variety of neurological diseases." (PMID 38915946, 2024). "In addition, the modulatory effects of canagliflozin on toll-like receptor 4/NLRP3 inflammasome signalling might potentiate its anti-inflammatory effects in various neurological disorders." (PMID 39596990, 2024). "Therefore, whether H2S can improve nervous system diseases by regulating autophagy/NLRP3 inflammasome is a topic worthy of study in the future." (PMID 36144282, 2022). "Furthermore, the mitophagy-mediated maintenance of mitochondrial homeostasis may limit NLRP3 inflammasome hyperactivation and its consequences in various neurological diseases." (PMID 36231090, 2022). "It was demonstrated that SAA might play an important role in the pathogenesis of neurological disorders by up‐regulating the expression of the cytokine interleukin‐1β (IL‐1β), which is mediated by the Nod‐like receptor protein 3 (NLRP3) inflammasome, cathepsin B, and caspase‐1." (PMID 34018701, 2021). "Finally, we discuss the targeting of NLRP3 in neurological diseases and present some examples of NLRP3 inhibitors that could be used in neurological disorder treatments." (PMID 31892810, 2019). "First, as most studies on miRNA in the treatment of chronic inflammation-mediated nervous system diseases focus on NF-κB signaling, MAPK signaling, and NLRP3 inflammasome pathways, more attention should be paid to discover new signaling pathways." (PMID 37637999, 2023). "Not only NLRP3 and NLRC4 but also NLRP1 inflammasome were shown to have a role in neurological diseases." (PMID 31892810, 2019).
neurological diseases (continued). "In addition, we review a series of promising therapeutic approaches that target the NLRP3 inflammasome signaling including anti-IL-1 therapy, small molecule NLRP3 inhibitors and other compounds, however, these approaches are still experimental in neurological diseases." (PMID 28337127, 2017). "Even though the efficacy of NLRP3 downstream inhibitors have been established against autoinflammatory conditions, there are no reports on their clinical uses or clinical trials, for neurological disorders." (PMID 38421496, 2024). "Although related themes of bibliometric studies were conducted, including inflammasome in neurological diseases, there is no bibliometric analysis focusing on NLRP3 inflammasome in ALI/ARDS so far." (PMID 36618363, 2022). "We show that the NLRP3 inflammasome, a key mediator of neurologic disease in mice, is not upregulated in pigs, further supporting its important role in JEV infections." (PMID 33097065, 2020). "However, no drugs directly targeting NLRP3 inflammasome are available for clinical use in neurological disorders at present." (PMID 36160384, 2022). "Thus, IGF-1 is a promising therapeutic option for the treatment of various neurological disorders through regulation of multiple neuroprotective signaling pathways, including Ras/Erk1/2, PI3K/MAPK/Akt/mTOR, Ca2+/CaMK II and IV, CREB, C/EBPβ, and GSK3B/NF-kB/NLRP3." (PMID 36691085, 2023). "Upregulated NLRP3 expression may enhance caspase-1-mediated inflammatory cascades and further stimulate the production of downstream inflammatory molecules, including IL-1β, IL-6, and TNF-α, all of which lead to an inflammatory response in a variety of neurological diseases." (PMID 36364939, 2022).
infectious disease (65 papers, 2012 to 2025). A disorder directly resulting from the presence and activity of a microbial, viral, or parasitic agent in humans. "Taken together, these results highlight the contributions of NLRP3 inflammasome and tight junction ZO-1 to endothelial pathophysiology in infectious diseases caused by tick-borne cytosolic-replicating bacteria." (PMID 39679710, 2025). "In vitro, macrophages with TET2-repressing mutations expressed the pro-inflammatory IL-1β, IL-6 and inflammasome NLRP3 in a pattern typically associated with macrophage activation in infectious diseases." (PMID 36835370, 2023). "Though current knowledge of the mechanisms underlying the activity of lopinavir and favipiravir cannot be traced back to NLRP3 inflammasome activation, these drugs can be linked to certain infectious diseases in which Panx1 channels are involved." (PMID 35628472, 2022). "In this sense, it has been demonstrated that activated T cells display a complement C5 protein-dependent NLRP3 inflammasome assembly, which induces T helper 1 (Th1) responses, which are typically associated with autoimmune and infectious diseases." (PMID 36248890, 2022). "NLRP3 rs10754558 polymorphism (3’UTR region) has been studied in several infectious diseases (HIV-1 and HTLV1 infection), neoplastic processes, hematological diseases, inflammatory and autoimmune disorders." (PMID 34161370, 2021). "It is conceivable that the rather detrimental NLRP3 activity associated with higher age of humans requires a higher level of regulation than in lower species, where communicable diseases represent the higher health thread." (PMID 31324763, 2019). "The present study was designed as a case-control study in order to find out if genetic variations of the NLRP3 inflammasome are associated with susceptibility to severe infectious disease." (PMID 25400921, 2014). "Collectively, our findings provide compelling evidence that emodin effectively attenuates NLRP3-driven inflammation, establishing it as a promising candidate for the prevention of inflammatory and infectious diseases associated with aberrant NLRP3 inflammasome activation." (PMID 40520006, 2025). "Importantly, NLRP3 inflammasome-mediated IL-1β is required to drive an effective inflammatory response in infectious diseases triggered by pathogenic microorganisms." (PMID 32630207, 2020). "A deep understanding of how different signals adopt different channels to utilize several ion fluxes at the same time provides new knowledge of the immune pathogenesis of infectious diseases involving the NLRP3 inflammasome and the development of therapeutics." (PMID 40307577, 2025). "The NLRP3 inflammasome plays a pivotal role in infectious diseases by recognizing both endogenous and exogenous danger signals to promote inflammation; however, its excessive activation can instigate systemic hyperinflammation, further exacerbating damage." (PMID 40284982, 2025). "Dysregulated activation of the NLR family pyrin domain-containing 3 (NLRP3) inflammasome contributes to the pathogenesis of numerous inflammatory and infectious diseases; however, effective targeted therapies remain elusive." (PMID 40520006, 2025). "Collectively, these results not only establish the molecular underpinnings of emodin's anti-inflammatory activity, but also highlight its therapeutic potential in treating NLRP3-driven inflammatory and infectious diseases." (PMID 40520006, 2025). "The expression of NOD-like receptor 3 (NLRP3) inflammasome is a typical feature of infectious diseases and a critical protein involved in pyroptosis." (PMID 36793340, 2022). "This principle of comparing the reaction of NLRP3-proficient and deficient THP 1 cells as an indicator of specific NLRP3 activation has been used in infectious disease research and has already been described for silica particles." (PMID 36008988, 2022).
infectious disease (continued). "As an important component of innate immunity, the NOD-like receptor 3 (NLRP3) inflammasome plays an important role in host immune response and the occurrence and development of infectious diseases." (PMID 36151570, 2022). "Today it is evident, that many antibiotics commonly used for treatment of infectious diseases, can induce or reduce NLRP3 activity by targeting mitochondrial processes." (PMID 34577552, 2021). "The inflammasome most studied in sterile inflammation and non-communicable disease is the NLRP3 inflammasome." (PMID 33255820, 2020). "Being composed of nucleotide‐binding domain‐like receptor protein 3 (NLRP3), ASC, and caspase‐1, the NLRP3 inflammasome plays an important role in the host response to infectious disease." (PMID 32697385, 2020). "A better understanding of the mechanism that governs the NLRP3 inflammasome will facilitate the development of more effective interventions for the treatment of infectious diseases and increase our understanding of viral pathogenesis." (PMID 30761102, 2019). "The NLRP3 inflammasome promotes the pathogenesis of metabolic, neurodegenerative and infectious diseases." (PMID 30944389, 2019). "Therapeutically, IL-10 can be specifically targeted to either attenuate or activate NLRP3 inflammasome in the treatment of several autoinflammatory and infectious diseases." (PMID 26412089, 2015). "Moreover, it is also known that, besides infectious diseases, NLRP3 activation plays a central role in autoimmune and inflammatory diseases." (PMID 40227443, 2025). "In non-infectious diseases such as tIRI, the damage-associated molecular patterns (DAMPs) like ROS, OS, and ATP orchestrates the activation of the NLRP3 inflammasome, which causes non-infectious “sterile” inflammation." (PMID 36671008, 2023). "Due to similar links to inflammation, NLRP3 inflammasome activation, and Panx1-related infectious diseases, the proposed group of drugs could hold great potential to uncover additional Panx1 channel inhibitors." (PMID 35628472, 2022). "As we know, reactive oxygen species, mitochondrial damage, infectious diseases, and episodes of MI could activate NLRP3." (PMID 36387353, 2022). "Therefore, NLRP3 and autophagy are potential treatment targets for use in combating S.pn-based infectious diseases." (PMID 35111047, 2021). "NETs and NLRP3 inflammasome are formed in a similar set of human disorders and infectious diseases." (PMID 34122445, 2021). "Although activation of the NLRP3 inflammasome is a host defense mechanism to eliminate invading pathogens in infectious diseases, excessive activation of the NLRP3 inflammasome is also central to aberrant inflammation, progression to tissue injury, and organ dysfunction." (PMID 32265704, 2020). "However, in untreated infected mice, changes of levels of NLRP3, a target protein of NF-κB that plays a key role in immune responses to infectious diseases, paralleled changes of phosphorylated NF-κB levels, leading to cleavage of pro-caspase-1 and triggering of the inflammatory cascade." (PMID 34950611, 2021). "NLRP3 is a drug target of significant interest to the pharmaceutical industry, with potential for the treatment of several inflammatory diseases including cancer, autoimmune diseases, metabolic disorders, cardiovascular disease, CNS diseases, and infectious diseases including COVID-19." (PMID 33255820, 2020). "However, inhibition of NLRP3 inflammasome in females is not always protective; in some cases, females are even more likely to develop infectious diseases." (PMID 34150848, 2021).
kidney (52 papers, 2012 to 2025). "In previous studies, it has been shown that a new mouse model can lead to excessive activation of NLRP3 inflammatory bodies in hepatocytes, thereby shortening the survival period of mice and causing poor growth and severe liver inflammation." (PMID 35566282, 2022). "Several primary renal diseases and systemic diseases affecting the kidney are associated with NLRP3 inflammasome/IL-1β/IL-18 axis activation." (PMID 24450291, 2014). "Additionally, the NLRP3 inflammasome may enhance the impact of other carcinogenic risk factors associated with urogenital cancers." (PMID 40718836, 2025). "RAPA eliminates excessive ROS, inhibits NF-κB nuclear translocation and down-regulates the TXNIP/NLRP3 axis, consequently suppressing ROS-mediated NLRP3 inflammasome activation, which may be the underlying mechanism of the protective effect of autophagy on realgar-induced liver injury." (PMID 35628508, 2022). "A recent study found that P2X4 in an ischemia–reperfusion (I/R)-induced AKI mouse model triggers kidney inflammation and renal cell apoptosis by activating the NLRP3 inflammasome." (PMID 41357229, 2025). "This review has summarized current advances in understanding the composition, activation mechanisms, functional heterogeneity, and therapeutic targeting potential of the NLRP3 inflammasome in urogenital cancers." (PMID 40718836, 2025). "H2S reduces pyroptosis and alleviates acute kidney or lung injury by suppressing the NLRP3 inflammasome." (PMID 38613798, 2024). "NLRP3 is upregulated and activated in murine lung IR, and the selective inhibition of the NLRP3 inflammasome attenuates IRI." (PMID 38074089, 2023). "Our findings underscore a novel mechanism of Caspase 6 mediated RIPK1-IκBα interaction in regulating macrophage NEK7/NLRP3 function and hepatocytes ferroptosis, which provides therapeutic targets for clinical liver IR injury." (PMID 37828624, 2023). "As a result, MAMPs originating from the gut, such as lipopolysaccharides or microbial RNA, can enter the portal circulation and reach the liver, activating NLRP3 inflammasome and aggravating liver inflammation and fibrosis." (PMID 36969233, 2023). "The previous studies have shown that EVA1A suppresses NLRP3 activation to improve liver ischemia-reperfusion injury through induction of autophagy in Kupffer cells." (PMID 35743108, 2022). "TLYS treatment reduced the expression of NLRP3 and caspase-1 in rat kidney tissues, as well as the expression of inflammatory factors, and the interstitial fibrosis of the kidney." (PMID 35873572, 2022). "In the present study, we detected the cellular localization of NLRP3 inflammasomes in a transient middle cerebral artery occlusion (tMCAO) rat model and a transwell co-culture cell system under oxygen-glucose deprivation/reoxygenation (OGD/R) conditions." (PMID 30153825, 2018). "In summary, in this study, we established a key in vivo role for IL-1β in lung IR inflammation through the activity of the NLRP3 inflammasome." (PMID 29163464, 2017). "The aim of this study was to evaluate the role of NLRP3 inflammasome on BU/CY-induced liver inflammation in mice after HSCT." (PMID 26635145, 2015). "STING―ER stress―mtROS―NLRP3 inflammasome―acute kidney injury." (PMID 41153813, 2025). "Building upon these observations, we hypothesize that F. nucleatum contributes to colorectal carcinogenesis through the induction of NLRP3-mediated inflammation and dysregulated autophagy." (PMID 40869140, 2025). "Given the potential of combining NLRP3-targeted therapies with immune checkpoint inhibitors, clinical trials should be designed to evaluate the safety and efficacy of this combination therapy in patients with advanced urogenital cancers." (PMID 40718836, 2025). "The activation of the NLRP3 inflammasome favors the onset of steatohepatitis and liver fibrosis." (PMID 39179677, 2024).